GSK3B (glycogen synthase kinase 3 beta)
Diseases named in the same sentence as GSK3B in open-access papers (continued):
Sharing a sentence is not in itself a finding about the gene and the disease.
tumor (continued). "Even other authors considered GSK3β as a tumor suppressor in CLL, as they showed that GSK3β inactivation by a deregulated SYK/PKCδ pathway stabilized the antiapoptotic Mcl-1 protein." (PMID 36050315, 2022). "The concept translated to the CAR T cell therapy field as Gsk3β inhibition diminished exhaustion hallmarks in CAR T cells transferred to glioblastomas, resulting in prolonged tumor control." (PMID 35573704, 2022). "In prior reports, signaling through the PI3K/AKT/GSK3β/Snail axis has been reported to be integral to EMT induction and consequent tumor progression." (PMID 35574325, 2022). "qRT-PCR suggested that GSK3B, IL18 and VEGFA RNA expression level in tumor cells was remarkably higher in contrast with that in normal cells, in line with findings based on GEPIA platform." (PMID 36743929, 2022). "Further experiments showed that knockdown of MIF and SLC3A2 inhibited tumour growth and metastasis by promoting iron death and regulating the AKT/GSK‐3β pathway in vivo." (PMID 35567291, 2022). "In parallel with the in vitro data, the combination treatment significantly increased β-TrCP and GSK-3β expressions and reduced KRAS expression levels in the tumor tissues of these mice." (PMID 35305671, 2022). "To elucidate the molecular mechanism of TUBB4A/MYH9-mediated tumor progression, we assessed, with DU145 cells, the role of TUBB4A/MYH9 on the GSK3β/β-catenin signaling pathway by immunoblotting analysis." (PMID 35589707, 2022). "In summary, this study showed that chrysin inhibits tumor growth and VM by inhibiting HIF-1α, SPHK-1, and phospho-AKT/GSK-3β signaling in PC-3 cells under hypoxia." (PMID 36139362, 2022). "According to western blotting results, the protein expression levels of HIF‐1α, GSK‐3β, and PKM2 proteins were downregulated, indicating that the microenvironment of tumor hypoxia and abnormal metabolism was improved after administration." (PMID 39188744, 2022). "The AKT/GSK‐3β pathway is closely related to the EMT process and participates in various biological and pathological processes, such as tumour cell invasion and metastasis." (PMID 35567291, 2022). "In tumor tissue homogenates from mouse xenografts, protein expression of GIPC2, p-GSK-3β, and activated β-catenin were measured to verify the effects of GIPC2." (PMID 35347223, 2022). "Four genes (BDNF, PTGS2, GSK3B, and CTNNB1) were significantly upregulated and one gene (HPGD) was significantly downregulated in primary tumor tissues compared with adjacent normal tissues throughout all the five in silico datasets." (PMID 35054980, 2022). "The expression levels of proteins associated with the cell cycle (CDK4, CDK6 and cyclin D1), proliferation (Ki67 and PCNA) and the pathway (GSK-3β, p-GSK-3β, β-catenin) in tumor tissue samples were determined using western blotting." (PMID 34719320, 2022). "For example, lncSNHG5 works as a ceRNA by binding with miR-26a-5p, miR-132-3p or miR-154-5p to increase PCNA, GSK3β and CREB5 expression to drive cell proliferation, migration and metastasis of tumor cells 39-41." (PMID 36438499, 2022). "In conclusion, we identified TTYH3 regulates tumor development and progression via MK5/GSK3-β/β-catenin signaling in HCC and promotes itself expression in a positive feedback loop." (PMID 35844789, 2022). "Knockdown of both MIF and SLC3A2 inhibited tumour growth and metastasis via the AKT/GSK‐3β pathway in vivo." (PMID 35567291, 2022). "In CRC, YTHDF2 can increase the m6A modification of GSK3β mRNA, reduce the stability of GSK3β mRNA, and promote its degradation, which induces CRC cell proliferation and tumor progression." (PMID 35155557, 2022). "Therefore, these two studies suggest that GSK-3β could act as a tumor suppressor in CLL cells." (PMID 35681507, 2022). "Persistently inactive GSK3β has been found in various cancers, including TNBC, suggesting that p‐GSK3β at Ser9 has an oncogenic role in neoplastic disease." (PMID 35090098, 2022).
tumor (continued). "Active GSK3β binds to CK1 (Casein Kinase 1), APC (Adenomatous Polyposis Coli), AXIN1 and other members of the destruction complex to inhibit tumor development by phosphorylation and subsequent degradation of the oncogenic β-catenin protein." (PMID 35814427, 2022). "The application of this compound hindered tumor development and decreased the production of phosphorylated LPR6, phosphorylate and unphosphorylated DVL2, Ser9 phosphorylated GSK3β, active β-catenin, and cyclin D1." (PMID 35509712, 2022). "On the other hand, Gepia database revealed that in CC tumor tissues, RSF-1 expression is positively correlated with VEGFA, AKT1 and GSK3β expression." (PMID 36056431, 2022). "By contrast, high levels of GSK3β lead to reduced levels of GCN5 protein and LIFR‐K620 acetylation in PTEN WT tumours." (PMID 35172032, 2022). "Increased expression of LUCAT1 induces tumor cell growth and development by regulating the AKT/GSK3β signaling pathway." (PMID 36483915, 2022). "Overall, our study demonstrated that circLIFR acts as a tumor suppressor in HCC by regulating miR-624-5p and inactivating the GSK-3β/β-catenin signaling pathway." (PMID 35581180, 2022). "Phosphorylated GSK3β also increases SNAIL phosphorylation and nuclear export, activates, and promotes EMT, thus, the Akt/GSK3β pathway can affect EMT, which in turn affects tumor aggressiveness." (PMID 35609330, 2022). "The present study further demonstrates that the combination treatment modulates the expression of the tumor receptor signaling molecules, including TGF-β/TβR-2, AXL/Gas6, and Wnt/FZD/β-catenin/GSK-3β, in LLC1 tumor tissues." (PMID 36547898, 2022). "GSK3β inhibits immunomodulation by downregulating PD-L1 and LAG-3 checkpoints and increasing NK and T-cell tumor killing." (PMID 35402914, 2022). "Furthermore, the expression of proteins associated with tumor cell metastasis, including MMP7, MMP9, N-cadherin, vimentin and Snail, was significantly reduced, and the corresponding expression of proteins related to tumor cell apoptosis, such as caspase-3, PPAR and GSK-3β, was strongly increased." (PMID 35348430, 2022). "In vitro experiments using BLCA cell lines have shown that PI3K/Akt targets GSK-3β to regulate ZEB1 transcription and promote tumor invasion." (PMID 36061188, 2022). "We provide evidence that the anti-tumor efficacy of doxorubicin is enhanced by combination therapy with the MEK inhibitor trametinib, which strengthens GSK3β activity, thus blocking oncogenic signaling." (PMID 34433808, 2021). "Taken together, these results confirmed that PPA1 promoted tumor growth and metastasis via the PI3K/AKT/GSK3β signaling in vivo." (PMID 34595179, 2021). "Overall, the GSK-3β isoform appeared to be dominant over the GSK-3α isoform, although both isoforms were needed for optimal tumor rejections." (PMID 34142056, 2021). "The nodes glycogen synthetase kinase 3B (GSK3B) and SUFU become less involved in conveying the signal from the SMO to the tumor proliferation endpoint, and the tumor proliferation endpoint is reduced." (PMID 33754119, 2021). "Verince’s group reported that PDAC-derived EVs induced mitochondria-dependent apoptotic pathway in tumour cells through PTEN and GSK-3β activation, and downregulation of Hes-1 expression, a Notch-1 signalling pathway mediator." (PMID 34671031, 2021). "In this study, we tested combinations of standard-of-care therapy and 9-ING-41, a small molecule inhibitor of GSK-3β, in CRC cell lines and patient-derived tumor organoid models of CRC." (PMID 34955846, 2021). "CXCL5 recruits neutrophils into the TME, and the CXCL5/CXCR2 axis contributes to tumor growth and metastasis through the activation of PI3K/AKT/GSK-3β/Snail signaling to promote EMT." (PMID 34237033, 2021).
tumor (continued). "Specifically, the glycogen synthase kinase-3 beta (GSK-3β) has been recognized as anti-inflammatory and anti-tumor therapeutic target for steroidal saponins compounds derived from TTM." (PMID 34955834, 2021). "On the other hand, GSK3β activation down-regulates the Wnt/β-catenin signaling pathway, suppressing the EMT, tumor growth, CSC, and antiapoptotic activity in tumor cells." (PMID 33805447, 2021). "The alkaloid effectively downregulated TNIK, p-TNIK, β-catenin, F-actin and N-cadherin expression levels, and upregulated GSK-3β and E-cadherin in in vitro (MDA-MB-231 cells and MCF-7 cells) and in vivo models (Orthotopic 4T1 tumour bearing mouse)." (PMID 35095493, 2021). "In this report, we observed that SHP-1, a tumor suppressor, directly interacts with EGFR and suppresses its induction of Ras/Erk/GSK3β signaling and its downstream cell cycle and EMT signals." (PMID 34591414, 2021). "Culture protocols employing GSK-3b inhibitor TWS119 or, more recently, p38 inhibitor Doramapimod have been effectively employed to expand naïve tumor-specific T cells, while limiting their maturation." (PMID 33796916, 2021). "Glycogen synthase kinase-3β (GSK-3β) is a key protein in WNT pathway, also known as a tumor inhibitor." (PMID 35111682, 2021). "In normal mature cells, the Wnt pathway is turned off, and the destruction complex, which is composed of axin and its tumor suppressor partners APC, GSK-3β, and CK1, is formed." (PMID 34912456, 2021). "In this study, we show that SNHG12 binds to HuR to target ELAVL1 and YWHAZ, both of which are established tumor progression-related genes, and promotes GC cell proliferation via the YWHAZ/AKT/GSK-3β axis." (PMID 34195070, 2021). "Animal results indicated that GTW, especially GTW+DDP, significantly reduced tumour burden, prolonged the life span of mice, and down-regulated the levels of tumour markers CA125 and HE4 by regulating EMT through the ILK/AKT/GSK3β/Slug signalling pathway." (PMID 33531984, 2021). "Our study dissected the tumor-intrinsic PD-L1 pathway comprising PTP1B, p38-MAPK, GSK3β, and Snail that physically links PD-L1 to the regulation of the EMT status of TNBC cells." (PMID 33884962, 2021). "A recent study confirmed our results and suggested that inhibition of GSK3β decreased p-mTOR levels and downstream molecules, which were related to cell survival and growth in HCC cells and inhibited tumour growth in vivo." (PMID 34380537, 2021). "Staining showed CD4+ and CD8+ T cells to be scattered throughout the tumor region (respectively) however, significantly increased numbers of CD4+ T cells were apparent in the Gsk3b cKO sections as determined using Imagescope software." (PMID 34142056, 2021). "While our results confirm other studies that report the enrichment of stem cell features upon GSK3β inhibition, they seem to contradict reports of GSK3 inhibition leading to reduction of tumor growth and apoptosis." (PMID 34367990, 2021). "This tumor-intrinsic function of PD-L1, which is achieved via the protein tyrosine phosphatase1B (PTP1B)/p38-MAPK/glycogen synthase kinase 3β (GSK3β) axis and can be activated by PD-1 binding, regulates the aggressiveness of TNBC cells." (PMID 33884962, 2021). "Our data indicate a further role for WNK1 in the regulation of alternative splicing of tumor-related RAC1B, through complex formation with GSK3β and SRPK1." (PMID 33315986, 2020). "Higher expression of FGF19 in HCCs promotes tumor cell survival and has antiapoptotic effects that are exerted through the FGFR4-glycogen synthase kinase (GSK)3β-Nrf2 signaling cascade." (PMID 32104677, 2020). "Down-regulation of GSK-3β by siRNA and microRNA-129 or pharmacological inhibition of GSK-3β with lithium chloride, indirubins, 9-ING-41 and 9-ING-87 can inhibit tumor cell growth and metastasis 9-12." (PMID 31938062, 2020).
tumor (continued). "As a tumour suppressor in GBM, F‐box protein 16 proteasomally degrades nuclear β‐catenin, and subsequently βTrCP, in a GSK‐3β‐independent manner in GBM cells, leading to inhibition of proliferation." (PMID 32394588, 2020). "Collectively, these results indicate that GSK3β-mediated regulation of cell cycle progression via cyclin D1, CDK4 and cyclin B1 is responsible for tumor cell survival and proliferation in ESCC." (PMID 32678196, 2020). "In the objectives of this study, the effects of sCLU knockdown or overexpression were detected on chemoresistance, metastasis, tumor growth, CSC phenotypes and activity of AKT/GSK-3β/β-catenin axis." (PMID 32059741, 2020). "Intriguingly, the analysis showed that ASPH has considerable positive correlations in mRNA expression with GSK3B and CTNNB1 in most of normal/tumor tissues." (PMID 33015050, 2020). "On the other hand, LMP2A induces MTA1, which stimulates the downstream Wnt cascade, such as phosphorylation of glycogen synthase kinase 3-beta (GSK3β) and nuclear translocation of β-catenin, thereby LMP2A enhances EMT process and tumor invasion." (PMID 32872147, 2020). "We performed immunohistochemical staining to measure the expression of MACROD2, p-GSK-3β, β-catenin, and the EMT markers E-cadherin, vimentin, and N-cadherin in primary tumor tissues from the 380 patients in the FFPE cohort." (PMID 32257385, 2020). "Taken together, these results suggest that downregulation of PHLDA2 inhibits tumor growth and PI3K, thereby promoting autophagy and inhibiting EMT, in part through the PI3K/AKT/mTOR and PI3K/AKT/GSK-3β signaling pathways." (PMID 32385195, 2020). "In conclusion, GSK-3β exerts the dual role of drug resistance as a promoter or tumor suppressor, interacts with the PI3K/AKT pathway, regulates tumor proliferation and apoptosis, and ultimately relates to MDR." (PMID 32973135, 2020). "The authors determined HANR to be capable of binding GSKIP, thereby controlling GSK3β phosphorylation in HCC, potentially thereby promoting tumor growth." (PMID 32049807, 2020). "Inactivation of GSK-3β phosphorylation resulted in nuclear localization of β-catenin, which leads to the activation of GSK/β-catenin signaling pathway and promotes tumor metastasis." (PMID 33192529, 2020). "Blood flow and shear stress promote embryonic haematopoiesis and epithelial–mesenchymal transition (EMT) in the context of the tumor microenvironment by downregulating ERK and glycogen synthase kinase 3 beta (GSK3β)." (PMID 33019569, 2020). "In the MDA231 cells, LncRNA‐ZEB2‐AS1 promoted the proliferation and metastasis of tumor cells and triggered EMT via the PI3K/Akt/GSK3β/Zeb2 signaling pathway and F‐actin polymerization." (PMID 30825262, 2019). "Since FAM134B has strong tumorigenesis features and activates the Akt/GSK‐3β/β‐catenin axis, the role of FAM134B in tumor cell motility and metastasis were investigated." (PMID 30556279, 2019). "Increased GSK3β expression stimulated the β-catenin/TCF4/ZEB1/miR-200b network, which increased the downstream tumor stemness and EMT signals." (PMID 31754475, 2019). "This is the first report that kenpaullone can be utilized as a TMZ enhancer via GSK3β inhibition for patients with GBM and as a good candidate for tumor stem cell targeting therapy." (PMID 31296906, 2019). "The data showed that CB is a potent anti-tumor agent, and it further increased FOXO1-induced DDP chemosensitivity by antagonizing MYH9, which regulates GSK3β/β-catenin-mediated tumor stemness and EMT signals in NPC." (PMID 31754475, 2019).
tumor (continued). "The degradation of β-catenin is mediated by the phosphokinase activity of GSK-3β, which is inhibited through phosphorylation by activated phospho-AKT, another classic oncogenic kinase playing a remarkable role in tumor progression." (PMID 30717785, 2019). "Altogether, these results confirmed that FOXO1 suppresses tumor stemness and EMT signals by modulating the GSK3β/β-catenin pathway." (PMID 31754475, 2019). "It influences the expression of specific genes such as GSK-3β and APC (up-regulation) and β-catenin (down-regulation) which promote the apoptosis of tumor cells." (PMID 31905725, 2019). "GSK3‐β, a target of CHIR‐99021, is known to regulate tumor migration and invasion by controlling EMT." (PMID 30652076, 2019). "As one of the most important tumor-related signaling pathways, the activation of AKT/GSK-3β/β-catenin signaling pathway played a pivotal role in the development of tumors." (PMID 30828264, 2019). "The PI3K/AKT pathway is closely related to the proliferation, differentiation, apoptosis, migration, and adhesion of tumor cells involving multiple targets, including EGFR, BCL2, GSK3B, CDK2, and CDK4." (PMID 31406500, 2019). "APC plays a major role as a tumor suppressor by forming the beta-catenin destruction complex together with AXIN and GSK-3b." (PMID 31470906, 2019). "MiR-188-5p diminishes tumor suppressor PTEN expression, and further increases phospho-Ser9 of GSK3β to activate Wnt/β-catenin signaling in GC." (PMID 31138169, 2019). "Mechanistic studies demonstrated that FOXO1-induced miR-200b expression through the GSK3β/β-catenin/TCF4 network-mediated stimulation of ZEB1, which reduced tumor stemness and the epithelial–mesenchymal transition (EMT) signal." (PMID 31754475, 2019). "β-catenin-370aa competitively interacted with GSK3β and served as a decoy that prevented GSK3β from binding to full-length β-catenin, leading to antagonization of GSK3β-induced β-catenin degradation, which might shed light on the protein-coding potential of circRNAs during tumor progression." (PMID 31027518, 2019). "We demonstrated that FAM134B enhanced Akt activity with subsequent GSK‐3β phosphorylation, accumulation of β‐catenin, and stabilization of Snail, which promoted tumorigenesis, EMT, and tumor metastasis in HCC by experiments in vitro and in vivo." (PMID 30556279, 2019). "Compared with the paired non-tumor liver tissues, significant up-regulation of CCRK, p-GSK3βSer9/GSK3β, p-mTORSer2448/mTOR, p-4E-BP1Thr37/46/4E-BP1, p-S6KThr389/S6K, mSREBP1, G-CSF, p-STAT3Tyr705/STAT3, and AR were detected in HCC tissues (p < 0.05)." (PMID 30523261, 2018). "In contrast, GSK3β has been reported to be upregulated in NSCLC tissues and to positively regulate tumor cell proliferation." (PMID 29700285, 2018). "As the results show, large primary tumors in the cecum and widespread distribution of tumor foci in the abdomen were observed in the SW480/miR452 group, whereas primary tumors in the SW480/miR452 + GSK3β group (Left) were remarkably smaller." (PMID 30253791, 2018). "Herein, we identify RASAL2 as a novel tumor suppressor in RCC, and it can inhibit RCC angiogenesis via p-GSK3β/c-FOS/VEGFA pathway." (PMID 30158581, 2018). "Several studies have suggested possible roles of GSK-3β as a tumor suppressor gene in HCC, whereas, other studies have indicated that GSK-3β is a potential therapeutic target for this cancer." (PMID 29445085, 2018). "Mechanistically, we showed that FIBP bound to GSK3β, which inhibited phosphorylation of GSK3β at Tyr216 and activated β-catenin/TCF signaling to accelerate cell cycle and promote tumor growth." (PMID 30275459, 2018). "Preclinical studies of single and chronic oral dosing of AZD5363 in mice have demonstrated dose-dependent inhibition of AKT substrate phosphorylation (GSK3β and PRAS40), tumour cell proliferation, and tumour growth in xenograft models." (PMID 29541803, 2018).